SPINK1 (serine peptidase inhibitor Kazal type 1)
Diseases named in the same sentence as SPINK1 in open-access papers (continued):
Sharing a sentence is not in itself a finding about the gene and the disease.
prostate carcinoma (continued). "Molecular stratification of prostate cancer (PCa) based on genetic aberrations including ETS or RAF gene‐rearrangements, PTEN deletion, and SPINK1 over‐expression show clear prognostic and diagnostic utility." (PMID 25809148, 2015). "ERG and SPINK1 positive tumors have been proposed to describe discrete molecular subtypes of prostate cancer." (PMID 26172920, 2015). "More recently, overexpression of the trypsin inhibitor SPINK1 was found to define a second prostate cancer subtype mutually exclusive with ETS overexpression." (PMID 25749039, 2015). "SPINK1 is another gene that was predicted to be overexpressed, it plays a significant role in prostate cancer development." (PMID 22811706, 2012). "Prostate cancer from EA men often contains ERG fusion/ETS family fusions and SPINK1 mutations, which are not as commonly found in prostate cancer from AA men." (PMID 38566104, 2024). "Within the ventral prostate, we also uncovered two additional androgen-responsive luminal epithelial cell types, marked by Pbsn or Spink1 expression, which align with human luminal subsets and may define the origin of distinct prostate cancer subtypes." (PMID 39763898, 2024). "In addition, it has been shown that SPINK1 promotes the development and survival of tumor cells in prostate cancer by suppressing the activity of specific enzymes that are involved in apoptosis, also known as programmed cell death." (PMID 38093163, 2023). "experimentally showed that the human anti-SPINK1 antibody against prostate cancer could reduce tumor growth." (PMID 35924241, 2022). "SPINK1 in prostate cancer is considered to be a potential target of miR-32." (PMID 35223512, 2022). "Top enriched genes in cSCs included stem-cell-related genes PSCA, CD36, and SPINK1, among others not previously associated with prostate cancer stem-like cells." (PMID 34360875, 2021). "Moreover, SPINK1 reprograms the expression profile of prostate cancer cells, leading to prominent epithelial–endothelial transition (EET), a phenotypic switch mediated by EGFR signaling." (PMID 33916984, 2021). "Furthermore, the phenomenon was substantiated by another group showing the SPINK1-dependent increase in chemoresistance in the prostate cancer cell lines PC3, DU145, LNCaP and M12 treated with AG-1478 or cetuximab." (PMID 33916984, 2021). "Overexpression of miR-338-5p/miR-421 reduced ABCG2 transporter-mediated Hoechst 33,342 efflux in a side population analysis in prostate cancer, suggesting the potential modulation of SPINK1 in drug resistance, a finding proven by direct SPINK1 silencing using specific shRNA clones." (PMID 33916984, 2021). "Interestingly, SPINK1 modulates the tumor microenvironment, and its expression was specifically detected in the stromal cells of prostate cancer patients after chemotherapy." (PMID 33916984, 2021). "However, previous studies reported an interesting phenomenon, whereby some cell lines, such as a prostate cancer–derived cell line, 22RV1, and a colon cancer–derived cell line, WiDr, highly express SPINK1 even under normoxic conditions." (PMID 34747365, 2021). "SPINK1 is expressed largely in the pancreas, gastrointestinal tract, and urinary system and has been suggested to promote pancreatic cancer, colorectal cancer, and prostate cancer progression." (PMID 34202399, 2021). "The link between SPINK1 and increasing sphere formation ability in prostate cancer was also validated using the 22RV1 cell line and by regulating the expression of genes involved in stemness and epithelial-mesenchymal transition (EMT), including SNAI1 (SNAIL), SNAI2 (SLUG), and TWIST1." (PMID 33916984, 2021). "SPINK1 upregulation is found in ~10–25% of prostate cancers." (PMID 31959826, 2020).
prostate carcinoma (continued). "The gastrointestinal gene signature was orchestrated by the transcription factors HNFG4 and HNF1A; the induction of HNFG4 and HNF1A-mediated pathway is required to sustain the proliferation of SPINK1-overexpressing prostate cancer cells, independently of AR signaling." (PMID 31366128, 2019). "Some of these genes were already extensively studied in prostate cancer, mostly those upregulated in tumor tissue: SPINK1 (Top17, logFC 4.8), ETV4 (Top63, logFC 3.6), PCA3 (Top79, logFC 3.5), TDRD1 (Top86, logFC 3.4), AMACR (Top105, logFC 3.2), DLX1 (Top110, logFC 3.1), HOXC6 (Top268, logFC 2.3)." (PMID 31170942, 2019). "A recent study based on transcriptome analysis of prostate cancer tissues showed that SPINK1 overexpressin prostate cancers are characterized by a peculiar gene expression signature, involving the expression of genes typically expressed in the gastrointestinal tract, such as albumin gene." (PMID 31366128, 2019). "SPINK1 was overexpressed in an aggressive subtype of ETS-negative prostate cancers." (PMID 31366128, 2019). "SPINK1 tumor cell expression and possible prognostic value have been most studied in prostate cancer, where SPINK1 positive tumors form a subgroup of about 10–15% of prostate cancers." (PMID 30778387, 2019). "Interestingly, a recent study SPINK1-positive castrate resistant prostate cancer identified POU5F1/OCT4 as part of a gastrointestinal gene signature present in SPINK1-positive prostate cancer and regulated by HNF1A and its target gene HNF4G." (PMID 30074477, 2018). "Interestingly, Spink3, the mouse homolog of Spink1 which is known to promote aggressive prostate cancer in humans, was also affected by wafarin." (PMID 28099154, 2017). "Much additional work with large clinical datasets, such as ours, will be necessary to test whether molecular subtyping with ERG and SPINK1 will provide clinically or biologically meaningful information in prostate cancer." (PMID 26172920, 2015). "A second subtype, characterized by SPINK1 overexpression, accounts for 15% of prostate cancers." (PMID 25749039, 2015). "Monoclonal SPINK1 antibodies have shown efficacy in preclinical models, suggesting that SPINK1 inhibition may prove a beneficial treatment strategy in the 15% of prostate cancers positive for SPINK1 overexpression." (PMID 25749039, 2015). "The prostate cancer cell line 22Rv1 has an aggressive phenotype and highly expresses SPINK1." (PMID 23527199, 2013). "Therefore, there might be possible roles for assessment of ERG and SPINK1 expression in prostate cancer care in the future." (PMID 26172920, 2015). "Background and Objectives: Prognostic biomarkers in prostate cancer (PCa) include PTEN, ERG, SPINK1, and TFF3." (PMID 38256434, 2024). "Phosphatase and TENsin homolog (PTEN), Erythroblast transformation-specific–related gene (ERG), Serine protease inhibitor Kazal-type 1 (SPINK1), and Trefoil Factor 3 (TFF3) have been identified as important biomarkers for prostate cancer." (PMID 38256434, 2024). "SPINK1 expression and ETS fusion status are mutually exclusive, and SPINK1 outlier expression is an independent predictor of biochemical recurrence after prostate cancer resection." (PMID 35223512, 2022). "SPINK1 protein binds to EGFR and activates its downstream signals, leading to the progression of pancreatic cancer, prostate cancer, bladder cancer (BCa), pancreatic ductal adenocarcinoma and breast cancer cells." (PMID 35223512, 2022). "In SPINK1-positive prostate cancer cells, forced ectopic expression of miR-338-5p and miR-421 eliminated tumorigenic properties, including cell cycle progression, stem cell resistance and drug resistance, and the miR-338-5p/-421/SPINK1 pathway may be a valuable target for tumor therapy." (PMID 35223512, 2022). "In prostate cancer, EGFR was found to mediate SPINK1′s biological function when triggering the epithelial–mesenchymal transition." (PMID 33916984, 2021).
prostate carcinoma (continued). "In another report, it was found that 17% of prostate cancer cases with multifocal tumors showed both ERG and SPINK1 overexpression within different regions of either the same tumor focus or different foci, but not in the same tumor cells." (PMID 33634124, 2021). "In prostate cancer, EGFR signaling pathway induces SPINK1 trypsin inhibitor to promote EMT and overexpression of SPINK1 represents its aggressive form." (PMID 33298014, 2020). "Taken together, these findings highlight the predominant role of SPINK1 in EMT, stemness and drug resistance in prostate cancer." (PMID 31959826, 2020). "SPINK1 is similar on a structural point of view to EGF and activates the EGFR on the surface of prostate cancer cells, inducing their growth." (PMID 31366128, 2019). "We found that 79 of 20261 genes showed marked over-expression (outliers) in certain tumor samples, including 3 previously reported prostate cancer genes (ERG, ETV1, and SPINK1)." (PMID 28027300, 2016). "SPINK1 and ERG are expressed in 25% and 42.7% of primary prostate cancer cases, respectively." (PMID 35223512, 2022). "In primary prostate cancer, the SPINK1+/ERG- phenotype accounts for 12.5%, the SPINK1+/ERG+ phenotype accounts for 16.7%, the SPINK1-/ERG+ phenotype accounts for 25.0%, and the SPINK1-/ERG- phenotype accounts for 45.8% of cases, and all prostate cancers expressing SPINK1 or ERG show PTEN deletion." (PMID 35223512, 2022). "A study proposed that prostate cancer can be divided into different molecular subtypes, including mutually exclusive cancers with positive E-26 transformation-specific (ETS) gene fusion, overexpression of SPINK1, and E-cadherin deletion." (PMID 35223512, 2022). "SPINK1 was not a predictor of mortality or overall survival among prostate cancer patients who had undergone radical prostatectomy." (PMID 33916984, 2021). "In addition, the mutual exclusivity of SPINK1 expression and ETS fusion status had been reported in prostate cancer." (PMID 33916984, 2021). "In addition, SPINK1 plays an important role in reprogramming the expression profile of prostate cancer cells and contributes to EET in prostate cancer." (PMID 33916984, 2021). "Here, they show that whilst SPINK1 is transcriptionally repressed by androgen receptor and its co-repressor REST, it is upregulated after androgen-deprivation therapy, which leads to neuroendocrine differentiation of prostate cancer cells." (PMID 31959826, 2020). "Thus, six biomarkers, including ERG, AMACR, SPINK1, NKX3.1, GOLM1, and AR predict higher aggressiveness of AAM than CaM prostate cancers; then, CaM had triple-negative (ERG-negative/ETS-negative/SPINK-1-negative) disease (51% vs. 35%)." (PMID 31366128, 2019). "SPINK1 protein overexpression does not seem to be a predictor of recurrence or lethal prostate cancer amongst patients treated with radical prostatectomy." (PMID 31366128, 2019). "Another quantitative abnormality frequently observed among non-rearranged ERG prostate cancers (11%) is represented by SPINK1 protein overexpression." (PMID 31366128, 2019). "SPINK1 is commonly overexpressed in SPOP-mutant and other ETS-negative prostatic cancers." (PMID 29581876, 2018). "For instance, all 3 CTCs from patient 1 expressed high levels of SPINK1, a transcript and protein identified as elevated in TMPRSS2-ERG fusion negative prostate cancers and associated with aggressive prostate cancer." (PMID 23145101, 2012). "It has been demonstrated that ~10% of prostate cancer cases are SPINK1+/fusion− and that this profile can be detected via non-invasive urine assays." (PMID 22641253, 2012). "SPINK1 is emerging as a biomarker of a molecular subtype of prostate cancer, in the absence of gene rearrangements/fusions such as TMPRSS2:ERG." (PMID 22641253, 2012). "SPINK1 plays an important role in ETS rearrangement-negative prostate cancer." (PMID 35223512, 2022).
prostate carcinoma (continued). "miR-338-5-p and miR-421 have been shown to be downregulated in SPINK1+ subtype of prostate cancer (2-fold and 1-4-fold as compared to ERG+ subtype, respectively) and negatively regulate proliferation, invasion, and colony and foci formation ability in SPINK1+ cell line." (PMID 36429127, 2022). "Additionally, the serum SPINK1 level demonstrates its prognostic value, and a negative correlation of SPINK1 with disease-free survival was observed in prostate cancer." (PMID 33916984, 2021). "Because SPINK1 partially exhibits its neoplastic effects through its interaction with EGFR, EGFR inhibitors may be a potential targeted therapy for SPINK1-overexpressing prostatic cancers." (PMID 29581876, 2018). "However, by themselves, neither ERG nor SPINK1 appear to be useful biomarkers for prognostication of early stage prostate cancer." (PMID 26172920, 2015). "SPINK1 expression is tightly linked to 6q15- and 5q21-deleted ERG negative prostate cancers." (PMID 25825985, 2015). "In addition, the overexpression of serine peptidase inhibitor, Kazal type 1 (SPINK1), protein, although not defining a molecular subtype, has been reported in approximately 10% of primary prostate cancer and is both mutually exclusive from ETS rearrangements and associated with SPOP mutations." (PMID 35050902, 2022). "Over-expression of SPINK1 has been described in cancers lacking the TMPRSS2-ERG fusion and has been reported to identify a subset (approximately 5–10%) of prostate cancers that behave more aggressively." (PMID 26172920, 2015). "The aggressive 22RV1 prostate cancer cell line expresses SPINK1 and SPINK1 knockdown attenuates 22RV1 invasion, suggesting a functional role in ETS rearrangement-negative prostate cancers." (PMID 24281110, 2010).
pancreatic cancer (54 papers, 1986 to 2025). "SPINK1 is implicated in cancer progression, promoting growth and invasion in lung, colon, and pancreatic cancers." (PMID 40576306, 2025). "PGVs in the SPINK1 gene have also been associated with an increased risk in pancreatic cancer, although controversy exists over SPINK1 being the sole driver of this risk." (PMID 39932614, 2025). "This is exemplified in individuals with cystic fibrosis and patients with hereditary pancreatitis due to mutations in PRSS1 or SPINK1, who have an increased risk of pancreatic cancer due to chronic inflammation and related changes in the pancreas." (PMID 38539517, 2024). "In case of hereditary pancreatitis caused by mutations in the PRSS1, CFTR, SPINK1 genes, pancreatectomy becomes advisable, including for prevention of pancreatic cancer." (PMID 39896151, 2024). "Overexpression of the protein SPINK1 has been linked to enhanced invasiveness and metastasis in pancreatic cancer, presumably as a result of the activation of signaling pathways that drive cell motility and invasion." (PMID 38093163, 2023). "The SPINK1 pancreatic cancer pathway is thought to increase risk of pancreatic cancer by lowering the activation threshold of trypsin." (PMID 35202241, 2022). "It is well known that CP patients with PRSS1 or SPINK1 gene mutations belong to a high-risk group for pancreatic cancer, with an estimated risk 53–87 times higher than the normal population." (PMID 33375361, 2020). "We identified the point mutation of the splicing site in SPINK1 as the possible genomic risk factor of the pancreatic cancer patient." (PMID 30407536, 2019). "Canonical pathways that were inhibited with TSA include cell cycle/division pathways such as cell cycle control of chromosomal replication and kinetochore metaphase signaling pathway as well as ADM-promoting pathways such as PI3K/AKT and those associated with pancreatic cancer (e.g., Spink1)." (PMID 36055991, 2022). "SPINK1 was a poor prognostic marker in cohorts of glioma, head and neck cancer, liver cancer, pancreatic cancer, renal cancer, and gastric cancer, while patients with colorectal cancer, urothelial cancer, and ovarian cancer expressing high SPINK1 levels are associated with favorable outcomes." (PMID 33916984, 2021). "From the data of a cohort focused on patients with SPINK1 mutations, the cancer risk was 12-times higher in patients than in controls, and the cumulative rates of pancreatic cancer before 50, 60, 70, and 80 years of age were 0.8%, 11.9%, 27.7%, and 51.8%, respectively." (PMID 33375361, 2020). "Thus, although limited publications show relationships between the variant and pancreatic cancer, PreMedKB greatly helped us recognize the variation in SPINK1 as the genomic risk factor of this 49-year-old pancreatic cancer patient." (PMID 30407536, 2019). "Another limitation is that the published reports did not include or classify pancreatic fibrosis caused by autoimmune pancreatitis or pancreatic cancer, which, because they are thought to be trypsin-independent, would have been an important comparison group for SPINK1 N34S effects." (PMID 18414673, 2008). "C-di-AMP+Pg LPS treatment regulated five pathways not shown to be significantly regulated by other treatment groups, including SPINK1 pancreatic cancer pathway and cell cycle: G1/S checkpoint regulation pathway." (PMID 39669221, 2025). "As a secreted protease inhibitor of pancreatic trypsin, SPINK1 is frequently overexpressed in pancreatic cancer, contributing to its development and progression." (PMID 40576306, 2025). "On the other hand, the same analysis identified activation of serine peptidase inhibitor Kazal type I (SPINK1) pancreatic cancer pathway and leukocyte extravasation signalling in senescent but not in young HPMCs." (PMID 38830931, 2024).